CLEC1A (C-type lectin domain family 1 member A)
Synonyms: CLEC-1; CLEC1; MGC34328
Tractability: Antibody: its Gene Ontology location is reachable by antibodies, with high confidence; UniProt predicts a signal peptide or a membrane-spanning region.
Gene: Protein-coding gene on chromosome 12 (10,069,554 to 10,111,627, reverse strand). Ensembl gene ENSG00000150048.
Subcellular location: Membrane
Subcellular location (Human Protein Atlas): Plasma membrane; Cytosol
Gene Ontology:
Molecular function: protein binding; transmembrane signaling receptor activity
Biological process: cell surface receptor signaling pathway; signal transduction
Cellular component: plasma membrane; membrane
Genetic constraint (gnomAD): Loss-of-function variants: 28 observed, 25.08 expected, observed/expected ratio (o/e) 1.12, 90% interval 0.83 to 1.53. The upper end of that interval is the gene's LOEUF score, 1.53, which puts it in group 6 of 6, group 1 being the genes least tolerant of losing a copy. Missense variants: 352 observed, 315.91 expected, observed/expected ratio (o/e) 1.11, 90% interval 1.02 to 1.22. Synonymous variants: 105 observed, 113.24 expected, observed/expected ratio (o/e) 0.93, 90% interval 0.79 to 1.09.
Homologues: Orthologues: chimpanzee CLEC1A (99% identical), macaque CLEC1A (90% identical), rabbit CLEC1A (71% identical), guinea pig CLEC1A (70% identical), rat Clec1a (69% identical), mouse Clec1a (67% identical), pig CLEC1A (61% identical), zebrafish si:dkey-26c10.5 (15% identical), Drosophila melanogaster rgn (15% identical), zebrafish si:ch211-170d8.8 (12% identical), zebrafish si:ch211-193e13.5 (12% identical), Caenorhabditis elegans clec-146 (10% identical), and 1 more. Paralogues in human: CLEC12B (32% identical), CLEC12A (28% identical), CLEC1B (24% identical), OLR1 (23% identical), CLEC7A (22% identical), CLEC9A (18% identical), KLRD1 (16% identical), KLRF1 (16% identical), KLRG1 (16% identical), KLRC1 (15% identical), KLRC2 (15% identical), KLRK1 (15% identical), and 11 more.
Diseases named in the same sentence as CLEC1A in open-access papers:
CLEC1A is named in the same sentence as 9 diseases in open-access papers, as found by Europe PMC text mining. Sharing a sentence is not in itself a finding about the gene and the disease. The quoted sentences say what the papers report.
aspergillosis (2 papers, 2022 to 2023). Aspergillosis is an infection, growth, or allergic response caused by the Aspergillus fungus. "Genetic variation in CLEC1A is a risk factor for the development of Aspergillosis in immunosuppression." (PMID 36327221, 2022).
COVID-19 (1 paper, 2022). A disease caused by infection with severe acute respiratory syndrome coronavirus 2. "Both traits’ association signals colocalized with eQTLs for CLEC1A in multiple tissues (PPH4 ≥ 0.97/0.87 for eQTL colocalisation with COVID-19/SLE) in GTEx v8 data." (PMID 36327221, 2022). "Therefore the SLE and severe COVID-19 risk allele, being associated with reduced expression of CLEC1A, would be expected to exert a pro-inflammatory effect." (PMID 36327221, 2022). "The risk allele for severe COVID-19 is also risk for SLE and is associated with reduced expression of CLEC1A." (PMID 36327221, 2022).
cancer (5 papers, 2017 to 2023). A tumor composed of atypical neoplastic, often pleomorphic cells that invade other tissues. "Via CLEC1A, HRG also stimulates neutrophils to superior performance as seen in cancer-inhibiting N1-neutrophils, which exhibit prolonged longevity, implying that HRG may sustain neutrophils in an N1 state." (PMID 36142212, 2022).
tumor (4 papers, 2016 to 2024). "This cluster includes 3 inhibitory lectin receptors expressed on myeloid and/or NK cells (CLEC1A, KLRA1, KLRA3), KLRA10, which is closely related in structure to inhibitory Ly49C receptors, and MGL2, a marker for pro-tumor macrophages." (PMID 27515027, 2016).
CLEC1A also shares sentences with these, for which no sentence is quoted: Autoimmunity (1 paper); colorectal tumors (1); infection (1); lobular carcinoma (1); Sepsis (1).